TRAF5 (TNF receptor associated factor 5)
Description:
Adapter protein and signal transducer that links members of the tumor necrosis factor receptor family to different signaling pathways by association with the receptor cytoplasmic domain and kinases. Mediates activation of NF-kappa-B and probably JNK. Seems to be involved in apoptosis. Plays a role in mediating activation of NF-kappa-B by EIF2AK2/PKR.
Synonyms: RNF84; MGC:39780
Tractability: PROTAC: UniProt records ubiquitination sites on it; ubiquitination databases record sites on it.
Gene: Protein-coding gene on chromosome 1 (211,326,325 to 211,375,036, forward strand). Ensembl gene ENSG00000082512.
Subcellular location: Cytoplasm; Cytoplasm, cytosol
Subcellular location (Human Protein Atlas): Cytosol; Centrosome
Gene Ontology:
Molecular function: identical protein binding; protein binding; thioesterase binding; ubiquitin protein ligase activity; ubiquitin protein ligase binding; signaling adaptor activity; tumor necrosis factor receptor binding; zinc ion binding
Biological process: CD40 signaling pathway; positive regulation of canonical NF-kappaB signal transduction; tumor necrosis factor-mediated signaling pathway; cell surface receptor signaling pathway; extrinsic apoptotic signaling pathway via death domain receptors; inflammatory response; intrinsic apoptotic signaling pathway in response to DNA damage; regulation of canonical NF-kappaB signal transduction; signal transduction; cytokine-mediated signaling pathway; interleukin-17-mediated signaling pathway; mRNA stabilization; regulation of apoptotic process
Cellular component: centrosome; cytoplasm; cytosol; CD40 receptor complex; cytoplasmic side of plasma membrane; plasma membrane; tumor necrosis factor receptor superfamily complex
Genetic constraint (gnomAD): Loss-of-function variants: 45 observed, 61.54 expected, observed/expected ratio (o/e) 0.73, 90% interval 0.57 to 0.94. The upper end of that interval is the gene's LOEUF score, 0.94, which puts it in group 3 of 6, group 1 being the genes least tolerant of losing a copy. Missense variants: 541 observed, 685.79 expected, observed/expected ratio (o/e) 0.79, 90% interval 0.73 to 0.85. Synonymous variants: 205 observed, 250.78 expected, observed/expected ratio (o/e) 0.82, 90% interval 0.73 to 0.92.
Homologues: Orthologues: chimpanzee TRAF5 (99% identical), macaque TRAF5 (98% identical), dog TRAF5 (89% identical), rabbit TRAF5 (88% identical), pig TRAF5 (87% identical), guinea pig TRAF5 (87% identical), rat Traf5 (81% identical), mouse Traf5 (80% identical), tropical clawed frog traf5 (59% identical), Caenorhabditis elegans trf-1 (21% identical), Caenorhabditis elegans trf-2 (12% identical). Paralogues in human: TRAF3 (42% identical), TRAF2 (30% identical), TRAF4 (25% identical), TRAF6 (24% identical), TRAF1 (22% identical).
Diseases named in the same sentence as TRAF5 in open-access papers:
TRAF5 is named in the same sentence as 62 diseases in open-access papers, as found by Europe PMC text mining. Sharing a sentence is not in itself a finding about the gene and the disease. The quoted sentences say what the papers report.
melanoma (10 papers, 2018 to 2024). A malignant, usually aggressive tumor composed of atypical, neoplastic melanocytes. "We aim to explore the effect of histone deacetylase 3 (HDAC3) and miR‐495‐3p on epithelial‐mesenchymal transition (EMT) and oncogenicity of melanoma cells by regulating tumour necrosis factor receptor‐associated factor 5 (TRAF5)." (PMID 33048450, 2020). "TRAF5 has been found to regulate inflammation and apoptosis of atherosclerosis, steatosis and melanoma cells, and also plays an important role in regulating myocardial I/R injury." (PMID 39104549, 2024). "TRAF5 has been determined as an oncogene in some cancers, such as melanoma (Ma, Duan & Hao, 2020) and ovarian cancer." (PMID 37366426, 2023). "Inhibited HDAC3 elevated miR‐495‐3p to suppress EMT and oncogenicity of melanoma cells by reducing TRAF5." (PMID 33048450, 2020). "Except for in vitro experiments, we also conducted in vivo experiment to probe into the roles of HDAC3, miR‐495‐3p and TRAF5 in melanoma cell growth." (PMID 33048450, 2020). "It was revealed that suppression of TRAF5 was able to inhibit proliferation while induce apoptosis of melanoma cells, while the target relation between miR‐495‐3p and TRAF5 is little known." (PMID 33048450, 2020). "Pearson correlation analysis was used to further verify the relationships between expression of HDAC3 and miR‐495‐3p/TRAF5 in the development of melanoma." (PMID 33048450, 2020). "As for the effect of TRAF5 on biological processes of melanoma cells, Li et al16 have identified that the repression of TRAF5 was accompanied by inhibited proliferation and enhanced apoptosis of melanoma cells." (PMID 33048450, 2020). "miR-26b deregulated in melanoma and targeted the TRAF5–MAPK signaling pathway, inhibiting the growth of melanoma cells." (PMID 32219065, 2020). "In summary, we demonstrated that reduced HDAC3 was able to up‐regulate miR‐495‐3p to suppress malignant behaviours of melanoma cells, thereby decelerating the development of melanoma with the involvement of TRAF5." (PMID 33048450, 2020). "We further discussed the role of HDAC3/miR‐495‐3p/TRAF5 in the biological functions of melanoma cells in vivo and in vitro using MTT assay, colony formation assay and subcutaneous tumorigenesis in nude mice." (PMID 33048450, 2020). "A recent study reported that TRAF5 is targeted by miR-26b and participates in melanoma cell proliferation and apoptosis by regulating MAPK activation." (PMID 31011336, 2019). "In addition, we demonstrated that inhibited HDAC3 enhanced miR‐495‐3p to restrict EMT in melanoma by silencing TRAF5." (PMID 33048450, 2020). "Additionally, Li et al16 demonstrated that the expression TRAF5 was higher in melanoma tissues than in normal tissues." (PMID 33048450, 2020). "In melanoma cells, TRAF5 overexpression could obviously counteract the anti-proliferative effects of tumor cells caused by elevated miR-26b expression." (PMID 31011336, 2019). "In conclusion, our study demonstrates that reducing the expression of TRAF4, TRAF5, or TRAF6 significantly improves the sensitivity of human ovarian cancer or melanoma cells to retinoic acid." (PMID 37389738, 2023). "B-cell neoplasms and human carcinomas such as melanoma, ovarian cancer, glioblastoma, and breast cancer have been found to implicate TRAF1, TRAF2, TRAF3, and TRAF5." (PMID 37389738, 2023). "Levels of HDAC3, miR‐495‐3p and TRAF5 in melanoma tissues and pigmented nevus tissues were determined, and the predictive roles of HDAC3 and miR‐495‐3p in prognosis of melanoma patients were measured." (PMID 33048450, 2020). "Recently, miR-26b-5p has been shown to target the MAPK and AKT/mTOR signaling pathways by binding to the 3′ UTR of TRAF5 or TRIM44, respectively, which are involved in the malignant progression of melanoma cells." (PMID 32825219, 2020).
melanoma (continued). "Our results revealed that down‐regulated HDAC3 elevates miR‐495‐3p to suppress malignant phenotypes of melanoma cells by inhibiting TRAF5, thereby repressing EMT progression of melanoma cells." (PMID 33048450, 2020). "The melanoma cells were screened and transfected with relative oligonucleotides and plasmids, and the expression of HDAC3, miR‐495‐3p and TRAF5, and phenotypes of melanoma cells were gauged by a series of assays." (PMID 33048450, 2020). "This study was designed to investigate effect of the HDAC3/miR‐495‐3p/TRAF5 axis in the development of melanoma, and we found that the inhibition of HDAC5 has the ability to elevate miR‐495‐3p to restrain the progression of melanoma by reducing TRAF5." (PMID 33048450, 2020). "Additionally, inhibiting TRAF4, TRAF5, or TRAF6 improved retinoic acid sensitivity and reduced colony formation in ovarian cancer and melanoma cells." (PMID 37389738, 2023). "Our results suggested that suppressing TRAF4, TRAF5, or TRAF6 can decrease the proliferation of ovarian cancer and melanoma cells and improve the sensitivity of these cells to retinoic acid treatment, probably by regulating cell apoptosis-related signaling pathways." (PMID 37389738, 2023). "Targeting TRAF4, TRAF5, or TRAF6 could be a promising strategy for inhibiting ovarian cancer and melanoma cell proliferation." (PMID 37389738, 2023). "In this study, we found that TRAF4, TRAF5, and TRAF6 were upregulated in several TCGA cancer cohorts and cancer cell lines, especially in ovarian cancer and melanoma cell lines, indicating their potential correlation with retinoic acid sensitivity in these cells." (PMID 37389738, 2023). "We aim to explore the impact of HDAC3/miR‐495‐3p/TRAF5 axis on melanoma, and we supposed that HDAC3 may mediate miR‐495‐3p to regulate the biological processes of melanoma cells by modulating TRAF5." (PMID 33048450, 2020). "HDAC3 and TRAF5 were increased while miR‐495‐3p was decreased in melanoma cells and tissues, and the low expression of miR‐495‐3p as well as high expression of HDAC3 indicated a poor prognosis of melanoma patients." (PMID 33048450, 2020).
colorectal cancer (9 papers, 2020 to 2025). A primary or metastatic malignant neoplasm that affects the colon or rectum. "On the other hand, the miR-141-3p has been found acting as a tumor-suppressing miRNA, inhibiting the cancer cells progression via directly targeting of tumor necrosis factor receptor-associated factor 5 (TRAF5) in colorectal cancer tissues and cell lines." (PMID 33413466, 2021). "We found that NCTD downregulates TRAF5 expression, subsequently inhibiting the phosphorylation of IκBα and p65 in colorectal cancer cells, thereby affecting their growth and survival." (PMID 40003916, 2025). "The whole-transcriptome sequencing and bioinformatics analysis identified TRAF5 as a key target for NCTD’s action against colorectal cancer." (PMID 40003916, 2025). "Further, an investigation has indicated the necroptosis-inhibitory role of TRAF5 in colorectal cancer." (PMID 37366426, 2023). "For example, the down-regulation of TRAF5 can inhibit the progression of colorectal cancer by suppressing the proliferation, migration, and invasion of cancer cells." (PMID 37366426, 2023). "miR-141-3p inhibits cell proliferation, migration, and invasion by targeting TRAF5 in colorectal cancer." (PMID 33204711, 2020). "Whole-transcriptome sequencing showed that TRAF5 was closely related to NCTD in colorectal cancer." (PMID 40003916, 2025). "TRAF5 is a direct target of miR-873 in colorectal cancer, inhibiting cancer cell proliferation." (PMID 40003916, 2025). "MiR-141-3p could suppress colorectal cancer cell growth and metastasis via targeting TRAF5." (PMID 32092085, 2020). "In colorectal cancer, METTL3 inhibits TRAF5 expression by reducing TRAF5 stability." (PMID 37996892, 2023).
atherosclerosis (8 papers, 2017 to 2025). A disease characterized by the build-up of fatty material and calcium deposition in the arterial wall resulting in partial or complete occlusion of the arterial lumen. "In conclusion, our study identified TRAF5 as a diagnostic marker of necroptosis-related atherosclerosis that can assess plaque stability." (PMID 37330462, 2023). "This study identified a diagnostic marker of necroptosis-related atherosclerosis, TRAF5, which can also be used to diagnose and assess atherosclerotic plaque stability." (PMID 37330462, 2023). "A PCSK9 inhibitor was found to mitigate atherosclerosis by modulating the small nucleolar RNA host gene 16 (SNHG16)/enhancer of zeste homolog 2 (EZH2)/TNF receptor-associated factor 5 (TRAF5) axis, thereby restraining the migration, proliferation and formation of foam cells by VSMCs." (PMID 40354375, 2025). "Consistently, TRAF5-deficient mice present with increased atherosclerosis, an effect likely caused by enhanced VCAM-1-dependent leukocyte migration and enhanced expression of MCP-1 and C-X-C motif ligand 1 (CXCL1), resulting in accelerated leukocyte recruitment into atherosclerotic lesions." (PMID 35252400, 2022). "TRAF5 reduces atherosclerosis and improves cardiometabolic risk factors." (PMID 35252400, 2022). "In vivo data suggest a negative regulatory role for TRAF5, as knocking out TRAF5 accelerates atherosclerosis in animal models." (PMID 37834170, 2023). "Interestingly, there have been studies showing that TRAF5 is associated with chronic inflammation-related diseases, which demonstrate that TRAF5 plays protective roles in atherosclerosis and obesity-induced non-alcoholic fatty liver disease or non-alcoholic steatohepatitis." (PMID 33224951, 2020). "Although inhibition of the CD40-TRAF-2/3/5 axis did not impact atherosclerosis, a knockout of TRAF-5 that was not specific for the CD40-binding site exacerbated atherosclerosis in mice by promoting leukocyte accumulation and foam cell generation in the plaque." (PMID 28676852, 2017).
autoimmune disease (5 papers, 2013 to 2025). A disorder resulting from loss of function or tissue destruction of an organ or multiple organs, arising from humoral or cellular immune responses of the individual to their own tissue constituents. "Therefore, the single nucleotide polymorphisms (SNPs) of TRAF5 on Chromosome 1 have been linked to autoimmune disorders, specifically rheumatoid arthritis (RA) and uveitis." (PMID 40136419, 2025). "Additionally, single nucleotide polymorphisms in TRAF5 were found associated with autoimmune diseases." (PMID 37389738, 2023). "TNF Receptor-Associated Factor 5 (TRAF5) has been shown to be associated with autoimmune disease." (PMID 24020968, 2013). "TRAF5’s roles in immune receptors have been suggested to be involved in inflammatory and autoimmune diseases in humans." (PMID 39596396, 2024). "TRAF5 and TRAF3IP2 have been reported to be associated with several autoimmune diseases." (PMID 24416204, 2014).
colitis (5 papers, 2016 to 2025). Inflammation of the colon. "To clarify TRAF5's influence on inflammatory bowel diseases (IBDs), we investigated TRAF5 deficiency's effect on dextran sulfate sodium- (DSS-) induced colitis." (PMID 27110068, 2016). "The loss-of-function experiments showed that TRAF5 deficiency could exacerbate DSS-induced colitis, characterized by striking body weight loss, a significantly increased DAI score, dramatic shortening of the colon, and more severe histological injury." (PMID 27110068, 2016). "Our data therefore demonstrated that TRAF5 deficiency could significantly exacerbate the severity of DSS-induced colitis." (PMID 27110068, 2016). "Colitis was induced in TRAF5 knockout (KO) mice and their wild-type (WT) littermates by administering 3% DSS orally for 7 days." (PMID 27110068, 2016). "In the present study, for the first time, we used 3% DSS to induce acute colitis in TRAF5 KO mice and their wild-type (WT) littermates to determine the specific roles of TRAF5 in the pathogenesis of IBDs." (PMID 27110068, 2016). "In summary, our study identified TRAF5 as an anti-inflammatory modulator in murine experimental colitis." (PMID 27110068, 2016). "It has been demonstrated that TRAF5 deficiency causes DDS-induced colitis; through RUNX1, TRAF5 regulates the immune response and controls the differentiation of Th1 and Th17 cells, contributing to the pathophysiology of colitis." (PMID 40093618, 2025). "Our data therefore demonstrated that the deletion of TRAF5 could significantly aggravate the severity of DSS-induced colitis." (PMID 27110068, 2016). "The colons of TRAF5 KO and WT mice were isolated for Western blot analysis to explore the potential molecular mechanisms underlying TRAF5 deficiency-mediated exacerbation of DSS-induced colitis." (PMID 27110068, 2016). "Furthermore, increased sensitivity to DSS-induced colitis was observed in Traf5-/- mice, and might be attributed to enhanced Th2 and IFN-γ/IL-17A co-producing CD4+T cell responses and CD4+T cell NF-κB activation under intestinal inflammation." (PMID 34956195, 2021). "Thus, we had reason to believe that the elevated level of Th2 cells and their specific cytokine IL-4 in the colons of TRAF5 KO mice might play proinflammatory roles during the development of DSS-induced colitis." (PMID 27110068, 2016). "The elevated expression of TRAF5 and the downstream NF-κB/MAPK activation mediated by TRAF5 subsequently promoted the inflammatory state of colitis." (PMID 38169708, 2023). "Although our data have demonstrated that NF-κB is activated in TRAF5 knockout mice during DSS colitis, it is not clear if this activation occurs in immune cells, epithelial cells, or both." (PMID 27110068, 2016).
colon cancer (4 papers, 2022 to 2025). "In summary, NCTD effectively inhibits the malignant proliferation of colon cancer cells by regulating the TRAF5/NF-κB signaling pathway and inducing programmed apoptosis, offering a novel treatment strategy." (PMID 40003916, 2025). "NCTD was further shown to regulate the TRAF5/NF-κB pathway to inhibit the malignant progression of colon cancer." (PMID 40003916, 2025). "Importantly, NF-κB can be a direct target of TRAF5 to protect from tumor cell death in some malignancies, such as gastric cancer and colon cancer." (PMID 37366426, 2023). "Consequently, miR-29b-3p suppresses 5-fluorouracil-promoted necroptosis of colon cancer cells and enhances its resistance by downregulating TRAF5." (PMID 36835100, 2023). "Additionally, miR-29b-3p is overexpressed, and TRAF5 is downregulated in colon cancer." (PMID 36835100, 2023).
rheumatoid arthritis (4 papers, 2013 to 2025). A chronic, systemic autoimmune disorder characterized by inflammation in the synovial membranes and articular surfaces. "In particular, mutations in the TRAF5 gene are associated with rheumatoid arthritis, ankylosing spondylitis, and uveitis." (PMID 39596396, 2024). "It has been demonstrated that TRAF5 polymorphisms are associated with susceptibility to rheumatoid arthritis (RA)." (PMID 24416204, 2014). "Recent studies have shown that TRAF5 polymorphisms are associated with rheumatoid arthritis (RA)." (PMID 24020968, 2013).